SURF1 (SURF1 cytochrome c oxidase assembly factor)
Diseases named in the same sentence as SURF1 in open-access papers (continued):
Sharing a sentence is not in itself a finding about the gene and the disease.
hypertrichosis (5 papers, 2020 to 2025). Excessive hair growth anywhere on the body. "A distinctive feature of SURF1-associated LS is the presence of hypertrichosis, which was detected in 65.6% (21/32) of patients in our series." (PMID 36675121, 2023). "Hypertrichosis is a frequent feature in LS patients with pathogenic variants in the SURF1 gene." (PMID 36675121, 2023). "In this regard, SURF1-related MD has a slightly more advantageous position due to the high frequency of hypertrichosis." (PMID 33134083, 2020). "Molecular assessment retrieved homozygous c.19_35dup17* (p.Ala13Cysfs*65) in SURF1, a gene typically related to a group of homogeneous symptoms (hypertrichosis and peripheral neuropathy), specific imaging findings (leukodystrophy), and high mortality in childhood." (PMID 37628588, 2023). "Although SURF1, SCO2 and some PDHA1-patients could be clinically well-defined, collection of such symptoms as median disease manifestation at 13 months, muscular hypotonia, hypertrichosis, ataxia and bilateral lesions in brainstem and/or basal ganglia are typical for the SURF1 gene cases." (PMID 36675121, 2023).
Ataxia (3 papers, 2017 to 2023). Ataxia refers to impaired coordination of voluntary muscle movement. "The patient with the SURF1 mutation showed normal development until age 2 years, when ataxia abruptly developed after a febrile illness." (PMID 35719373, 2022).
Encephalopathy (3 papers, 2018 to 2023). Encephalopathy is a term that means brain disease, damage, or malfunction. "Even if SURF1 loss-of-function mutations in humans are associated with severe early-onset encephalopathy, neuronal-specific silencing of Surf1 led to a milder phenotype, with normal development and no major signs of neuropathology." (PMID 36830747, 2023). "Conversely, in LS patients, SURF1 ablation causes a devastating, early-onset, invariably fatal encephalopathy associated with a typical isolated COX deficiency." (PMID 29601977, 2018).
leukodystrophy (3 papers, 2021 to 2023). Leukodystrophies are a group of rare, progressive, metabolic, genetic diseases that affect the brain, spinal cord and often the peripheral nerves. "Isolated leukodystrophy is unusual in patients with LS and SURF1 mutations, therefore other mitochondrial diseases, such as COX10 gene mutations and metabolic disorders, should be considered for diagnosis." (PMID 34943053, 2021).
Failure to thrive (2 papers, 2014 to 2018). Failure to thrive (FTT) refers to a child whose physical growth is substantially below the norm. "The clinical phenotype associated with the ablation of sSURF1 was extremely severe and characterized by growth retardation/arrest, failure to thrive and persistent tremors, supporting a fundamental role of SURF1 in post-natal survival of the pig." (PMID 29601977, 2018).
lactic acidosis (2 papers, 2023 to 2025). Metabolic acidosis characterized by the accumulation of lactate in the body. "Taken together, our data suggest that IT-administered AAV9/JeTI-hSURF1v2 restored endurance capacity and mitigated abnormal lactic acidosis during exhaustive exercise in Surf1 KO mice." (PMID 40893166, 2025).
Leber hereditary optic neuropathy (2 papers, 2024). Leber's hereditary optic neuropathy (LHON) is a mitochondrial neurodegenerative disease affecting the optic nerve and often characterized by sudden vision loss in young adult carriers. "However until this approach will become the standard diagnostic test we recommend that NDUFS6 together with other mitochondrial genes (including SCO2 and SURF1) should be included in panels for molecular genetic testing of neuropathies, intellectual disabillity and optic atrophy." (PMID 38217609, 2024).
Parkinson disease (2 papers, 2018 to 2024). A progressive degenerative disorder of the central nervous system characterized by loss of dopamine producing neurons in the substantia nigra and the presence of Lewy bodies in the substantia nigra and locus coeruleus. "There have been reports suggesting that mutations in the SURF1, COX20, and SCO2 genes, which are involved in the assembly of COX along with COA7, can result in a decrease in the activity of MRC complex IV, leading to dystonia or parkinsonism." (PMID 37750949, 2024).
Spastic paraplegia (2 papers, 2021 to 2023). Complete loss of the ability to move the lower limbs accompanied by spasticity of the lower limbs. "Pyramidal symptoms in the form of spastic paraplegia/tetraparesis are more typical for patients with mtDNA variants (54.0%) than the SURF1 gene cases (9.4%)." (PMID 36675121, 2023).
breast carcinoma (1 paper, 2025). "Additionally, twenty-one genes were observed to be targeted by variant-containing TCNEs with eQTL data from GTEx and the top three genes (LARS, SURF1, and MILR1) were significantly related to specific genetic variant loci of breast cancer (Storey’s Q<1×10−8)." (PMID 40427520, 2025).
cardioembolic stroke (1 paper, 2019). "CAV1, SURF1, PLEKHH2, ECD, BNIP1, CAV2 are found to be associated with cardioembolic stroke and Small vessel stroke in Europeans." (PMID 32038707, 2019).
cardiomyopathy (1 paper, 2014). A disease of the heart muscle or myocardium proper. "The COX activity in heart mitochondria from 40-week-old Surf1 knockout mice is reduced by ∼40%, but the respiration is unaffected, consistent with the absence of cardiomyopathy in these knockout mice." (PMID 24399447, 2014).
Charcot-Marie-Tooth disease (1 paper, 2025). An inherited degenerative disorder involving the peripheral nerves. "According to OMIM, SURF1 and ETFDH are associated with Charcot-Marie-Tooth disease (MIM #616684) and glutaric acidemia IIC (MIM #231680), respectively, with an autosomal recessive inheritance pattern." (PMID 40634996, 2025).
Cognitive impairment (1 paper, 2025). Abnormal cognition is characterized by deficits in thinking, reasoning, or remembering. "We previously hypothesized a role of IgG against DAB1, AIFM1, and SURF1 in cognitive impairment in COVID-19, given the well-described functions of the three proteins in neurogenesis and synaptic plasticity." (PMID 40995367, 2025).
COVID-19 (1 paper, 2025). A disease caused by infection with severe acute respiratory syndrome coronavirus 2. "We previously identified IgG autoantibodies targeting epitopes within brainstem proteins—disabled homolog 1 (DAB1), apoptosis-inducing factor 1 (AIFM1), and surfeit locus protein 1 (SURF1)—as markers of severe acute COVID-19." (PMID 40995367, 2025).
diabetes (1 paper, 2024). "Our findings also highlight variants in TBC1D32 and SURF1 that are associated with a higher risk of ESKD in individuals with diabetes." (PMID 38858654, 2024). "In particular for ESKD, we have identified three genes that might help identify people with a higher risk of developing this more aggressive form of kidney disease, both in the overall population (NUP210 and SLC4A1) and in people with diabetes (SURF1)." (PMID 38858654, 2024).
diabetic nephropathies (1 paper, 2024). "In UK-ROI, AGXT2-rs71615838 and SURF1-rs183853102 were associated with diabetic nephropathies, and TFB1M-rs869120 with eGFR." (PMID 38858654, 2024).
heart failure (1 paper, 2024). Inability of the heart to pump blood at an adequate rate to meet tissue metabolic requirements. "The molecular interconnections between heart failure and cancer risk may be mediated by ABO and SURF1, whilst the inverse relationship between heart failure and cancer risk may be influenced by methylation and tumor immune escape pathways." (PMID 38706896, 2024).
mitochondrial complex deficiency (1 paper, 2025). "Mutations in genes such as TTC19, SURF1, and PET100, which are associated with mitochondrial complex deficiency, as well as mutations in MT-ND3 linked to mitochondrial DNA-associated Leigh syndrome and NARP, were identified." (PMID 40336053, 2025).
Mitochondrial encephalopathy (1 paper, 2014). "LSCOX is a progressive infantile mitochondrial encephalopathy most frequently caused by mutations in SURF1, a nuclear gene encoding a protein located in the inner membrane." (PMID 25164807, 2014).
mitochondrial myopathies (1 paper, 2008). "It is important to emphasise that the presence of RRFs in the muscle, characteristic of mtDNA encoded mitochondrial myopathies, was extremely rare if not non-existent in the nuclearly encoded SURF1-LS muscle specimens, particularly in those carrying c.841delCT mutations." (PMID 17908801, 2008).
ophthalmoplegia (1 paper, 2013). Weakness or paralysis of at least one of the muscles controlling the movement of the eye. "We found that SURF1-deficient patients have a relatively homogenous phenotype which typically commences in late infancy with gastro-intestinal symptoms, followed by episodic neurological regression, ophthalmoplegia, movement disorder, finally leading to death from respiratory failure." (PMID 23829769, 2013).
pulmonary hypertension (1 paper, 2024). Increased pressure within the pulmonary circulation due to lung or heart disorder. "Additionally, studies have demonstrated a correlation between genetic variations in SURF1 and the occurrence of HF, pulmonary hypertension, and other related conditions." (PMID 38706896, 2024).
respiratory distress syndrome (1 paper, 2025). "ETFDH and SURF1 were prioritized due to their known roles in mitochondrial function and their relevance to the patient’s clinical features, including respiratory distress syndrome alongside HCM." (PMID 40634996, 2025).
Tremor (1 paper, 2020). An unintentional, oscillating to-and-fro muscle movement about a joint axis. "Although tremor has been frequently reported to be associated with SURF1 defects, no patient in our study presented with tremor." (PMID 33134083, 2020).
Zellweger syndrome (1 paper, 2013). "One patient from a consanguineous pedigree was found to have genetically confirmed Zellweger syndrome in addition to SURF1 disease (homozygous c.799_800delCT) and was excluded from further analyses." (PMID 23829769, 2013).
mitochondrial disease (14 papers, 2015 to 2025). "Animal models harbouring genetic changes in SURF1, the gene encoding the mitochondrial complex IV assembly factor is a well-established model of mitochondrial disease (mice, zebrafish and flies)." (PMID 34680998, 2021). "Individuals harboring POLG-, TYMP-, or MPV17- deletions or m.8993T>G and m.8993T>C mtDNA mutations, as well as those affected by SURF1-related mitochondrial diseases are at greater risk of developing peripheral neuropathy." (PMID 33383961, 2020). "Late detection of assembly factors with severe phenotype includes genes such as NDUFAF3, SURF1, TACO1, SCO1, LYRM7, or TIMMDC1, whose mutations are commonly found in patients with mitochondrial diseases (Fig. EV2F)." (PMID 40301572, 2025). "Using this design, we evaluated the response to PT1 using cells from patients with SURF1 and POLG-deficiency, two distinct causes of mitochondrial disease." (PMID 33052980, 2020). "Along this line, peripheral neuropathy as the leading symptom has already been reported in patients with mutations in some other primary mitochondrial disease genes (e.g. SCO2, SURF1) which are commonly associated with much more severe clinical presentations or even early death." (PMID 38217609, 2024). "In many cases, the treatment outcome is not promising for SURF1-associated LS since treatments are similar to those used for other mitochondrial diseases encoded by mutations in other genes." (PMID 34943053, 2021). "Mutations in SURF1 and POLG have been identified in patients with mitochondrial disease and hypertrophic olivary degeneration, but are not a consistent finding." (PMID 25887401, 2015). "Even though we do not know the exact mechanisms driving SURF1 overexpression toxicity or the toxicity related to other mitochondrial proteins, these observations warrant caution that extra care may be required with the design of mitochondrial disease gene therapies." (PMID 40893166, 2025).
cancer (3 papers, 2016 to 2025). A tumor composed of atypical neoplastic, often pleomorphic cells that invade other tissues. "This was accomplished by employing transcriptomics techniques to examine the functions of ABO and SURF1 in cancer." (PMID 38706896, 2024). "Regrettably, the current corpus of research pertaining to the correlation between SURF1 and both cancers and HF is inadequate." (PMID 38706896, 2024). "Additional investigation into the functions of ABO and SURF1 in cancer has yielded noteworthy findings." (PMID 38706896, 2024). "The results indicate that SURF1 may have a pro-oncogenic role in cancer, whereas ABO may have oncogenic properties." (PMID 38706896, 2024). "Conversely, reduced methylation levels of SURF1 were detected in BRCA patients compared to the normal group, indicating a plausible function of SURF1 as an oncogene promoter in cancer." (PMID 38706896, 2024).
movement disorder (3 papers, 2013 to 2020). Neurological conditions resulting in abnormal voluntary or involuntary movement, which may impact the speed, fluency, quality and ease of movement. "Among nuclear MDs, the SURF1 defect has been reported to be the most frequent molecular pathology associated with movement disorders." (PMID 33134083, 2020). "However, it has not been specified for a particular variant, approximately 52% of patients with SURF1 defects show movement disorders." (PMID 33134083, 2020).
neurodegenerative disease (1 paper, 2013). A disorder of the central nervous system characterized by gradual and progressive loss of neural tissue and neurologic function. "SURF1 deficient patients, on the other hand, usually survive into early childhood with a progressive neurodegenerative disease." (PMID 24472117, 2013).
SURF1 also shares sentences with these, for which no sentence is quoted: mitochondrial neurogastrointestinal encephalomyopathy (3 papers); neurological disorder (3); peripheral neuropathy (3); Barth syndrome (2); MELAS (2); neuropathies (2); tumor (2); alopecia totalis (1); Alpers syndrome (1); autosomal dominant optic atrophy (1); Bardet-Biedl syndrome (1); Bjornstad syndrome (1); cerebellar ataxia (1); cervical cancer (1); Chorea (1); condition of the brain (1); Dystonia (1); encephalomyopathies (1); esophageal SCC (1); Friedreich ataxia (1); glutaric acidemia IIc (1); insulinoma (1); kidney disease (1); metabolic disorders (1); mitochondrial cytopathy (1); mucolipidosis (1); multiple acyl-CoA dehydrogenase deficiency (1); myopathy (1); Neurodevelopmental delay (1); optic atrophy (1).
A further 8 diseases each share a sentence with SURF1 in 1 paper.